NBPF10 (NBPF member 10)
Synonyms: AG1; AB6
Tractability: PROTAC: ubiquitination databases record sites on it.
Gene: Protein-coding gene on chromosome 1 (146,064,711 to 146,229,000, reverse strand). Ensembl gene ENSG00000271425.
Subcellular location: Cytoplasm
Subcellular location (Human Protein Atlas): Cytosol; Primary cilium; Cytokinetic bridge; End piece; Golgi apparatus; Microtubules; Mid piece; Principal piece; Vesicles
Gene Ontology:
Molecular function: RNA binding
Cellular component: cytoplasm
Genetic constraint (gnomAD): Loss-of-function variants: 17 observed, 9.18 expected, observed/expected ratio (o/e) 1.85, 90% interval 1.18 to 1.97. That is too few expected variants to judge how well the gene tolerates losing a copy. Missense variants: 131 observed, 72.97 expected, observed/expected ratio (o/e) 1.8, 90% interval 1.55 to 1.97. Synonymous variants: 32 observed, 19.45 expected, observed/expected ratio (o/e) 1.65, 90% interval 1.22 to 1.95.
Homologues: Paralogues in human: NBPF20 (91% identical), NBPF19 (91% identical), NBPF14 (78% identical), NBPF26 (36% identical), NBPF12 (30% identical), NBPF9 (29% identical), NBPF8 (24% identical), NBPF1 (22% identical), NBPF11 (21% identical), NBPF15 (17% identical), NBPF3 (12% identical), NBPF4 (8% identical), and 1 more.
Diseases named in the same sentence as NBPF10 in open-access papers:
NBPF10 is named in the same sentence as 15 diseases in open-access papers, as found by Europe PMC text mining. Sharing a sentence is not in itself a finding about the gene and the disease. The quoted sentences say what the papers report.
breast carcinoma (3 papers, 2018 to 2023). "For example, we identified low-frequency mutations in NBPF10, which was previously reported to be the most significant gene involved in breast cancer, in both the primary and metastatic tumours of CRC4." (PMID 34507604, 2021).
cervical carcinoma (1 paper, 2021). A carcinoma arising from either the exocervical squamous epithelium or the endocervical glandular epithelium. "The increased sample size enabled identification of SMGs previously unreported in cervical carcinoma including NBPF10 (8%), RANBP2 (6%), MSN (6%), KRT8 (6%), POTEC (6%), ZC3H11A (4%), BMS1 (4%), GPX1 (3%), OTOP1 (3%), DNAH12 (2%), COIL (2%), TBC1D26 (2%), SPRED3 (2%), FAM115A (2%), and ARIH1 (1%)." (PMID 34620846, 2021).
cholangiocarcinoma (1 paper, 2021). A carcinoma that arises from the intrahepatic biliary tree (intrahepatic cholangiocarcinoma) or from the junction, or adjacent to the junction, of the right and left hepatic ducts (hilar cholangiocarcinoma). "Finally, six AS events, SLC38A10-44114-AT, IL18BP-17488-RI, NBPF10-5531-ES, THNSL2-54469-ME, FAM3A-90629-ES, and KIAA1432-85794-AT, were identified as independent risk factors for OS in cholangiocarcinoma." (PMID 34055632, 2021).
Mayer-Rokitansky-Küster-Hauser (MRKH) syndrome (1 paper, 2021). "This region also contains other NBPF family members, such as NBPF10, whose genetic variants were implicated in Mayer-Rokitansky-Küster-Hauser (MRKH) syndrome (OMIM # 277000), a disease associated with CS." (PMID 34440387, 2021).
neuroblastoma (1 paper, 2013). Neuroblastoma (NB) is the most common solid, extracranial childhood tumor. "MUC16 is a member of a large family of mucin coding genes and NBPF10 is from the neuroblastoma breakpoint family, which consists of 22 genes and pseudogenes that arose by gene duplication." (PMID 23940540, 2013).
ovarian carcinoma (1 paper, 2025). A malignant neoplasm originating from the surface ovarian epithelium. "Using independent ovarian cancer cohort (TCGA-OV) we also confirmed high frequencies of mutational alterations in the NBPF gene family including NBPF1, NBPF9, NBPF10, NBPF12 and NBPF14 (> 50%)." (PMID 41316472, 2025).
prostate tumors (1 paper, 2019). "HLA allele B08, for example, is predicted to strongly bind (<10 nM) the peptide containing mutation NBPF10 p.E3455K, a mutation found in uterine carcinosarcoma and prostate tumors." (PMID 31440245, 2019).
tumor (7 papers, 2014 to 2025). "Additionally, we observed that tumor-cell-specific isoforms had slightly more exons (paired t-test P-value = 0.01), particularly in genes with more than 20 exons such as NBPF10, VPS13C, and NBPF14." (PMID 37433798, 2023). "Among the 5,291 coding somatic mutations found in an aggregate of 240 matched tumour/normal samples, we found 26 overlapping variants in SH-SY5Y inside 24 genes among which 9 were rare amino-acid changing mutations inside 7 genes (ALK, FOXD4L1, HLA-DRB1, NBPF10, NBPF14, PABPC3, TEKT4)." (PMID 25528190, 2014).
neurogenetic diseases (1 paper, 2017). "As the examples, copy number change in NBPF10 is associated with multiple developmental and neurogenetic diseases, PABPC3 is involved in regulation of mRNA stability and translation initiation, and NPIPB11 is involved in forming nuclear pore complex." (PMID 28076423, 2017).
NBPF10 also shares sentences with these, for which no sentence is quoted: cancer (4 papers); metastatic tumors (2); endometrial cancer (1); melanoma (1); prostate (1); uterine carcinosarcoma (1).